DRICH1 (aspartate rich 1)
Synonyms: C22orf43; KB-208E9.1
Tractability: No criterion of Open Targets' tractability assessment is met for any kind of drug.
Gene: Protein-coding gene on chromosome 22 (23,608,452 to 23,632,321, reverse strand). Ensembl gene ENSG00000189269.
Subcellular location (Human Protein Atlas): Nucleoli; Nucleoplasm
Gene Ontology:
Molecular function: protein binding
Genetic constraint (gnomAD): Loss-of-function variants: 27 observed, 28.45 expected, observed/expected ratio (o/e) 0.95, 90% interval 0.7 to 1.31. The upper end of that interval is the gene's LOEUF score, 1.31, which puts it in group 5 of 6, group 1 being the genes least tolerant of losing a copy. Missense variants: 215 observed, 222.39 expected, observed/expected ratio (o/e) 0.97, 90% interval 0.86 to 1.08. Synonymous variants: 67 observed, 85.77 expected, observed/expected ratio (o/e) 0.78, 90% interval 0.64 to 0.96.
Homologues: Orthologues: chimpanzee DRICH1 (94% identical). Paralogues in human: C22orf42 (24% identical).
Diseases named in the same sentence as DRICH1 in open-access papers:
DRICH1 is named in the same sentence as 6 diseases in open-access papers, as found by Europe PMC text mining. Sharing a sentence is not in itself a finding about the gene and the disease.
DRICH1 shares sentences with these, for which no sentence is quoted: abscess (1 paper); acute vascular disorders of the intestine (1); chronic lymphocytic leukemia (1); diverticular disease (1); non-Hodgkin lymphoma (1); T-cell lymphoma (1).